TRGV9 (T cell receptor gamma variable 9)
Description:
V region of the variable domain of T cell receptor (TR) gamma chain that participates in the antigen recognition. Gamma-delta TRs recognize a variety of self and foreign non-peptide antigens frequently expressed at the epithelial boundaries between the host and external environment, including endogenous lipids presented by MH-like protein CD1D and phosphoantigens presented by butyrophilin-like molecule BTN3A1. Upon antigen recognition induces rapid, innate-like immune responses involved in pathogen clearance and tissue repair. Binding of gamma-delta TR complex to antigen triggers phosphorylation of immunoreceptor tyrosine-based activation motifs (ITAMs) in the CD3 chains by the LCK and FYN kinases, allowing the recruitment, phosphorylation, and activation of ZAP70 that facilitates phosphorylation of the scaffolding proteins LCP2 and LAT. This lead to the formation of a supramolecular signalosome that recruits the phospholipase PLCG1, resulting in calcium mobilization and ERK activation, ultimately leading to T cell expansion and differentiation into effector cells. Gamma-delta TRs are produced through somatic rearrangement of a limited repertoire of variable (V), diversity (D), and joining (J) genes. The potential diversity of gamma-delta TRs is conferred by the unique ability to rearrange (D) genes in tandem and to utilize all three reading frames. The combinatorial diversity is considerably increased by the sequence exonuclease trimming and random nucleotide (N) region additions which occur during the V-(D)-J rearrangements.
Synonyms: TCRGV9; V2
Tractability: Antibody: UniProt places it where antibodies can reach, with high confidence; UniProt predicts a signal peptide or a membrane-spanning region; its Gene Ontology location is reachable by antibodies, with medium confidence.
Gene: T-cell receptor variable (V) gene on chromosome 7 (38,317,017 to 38,318,861, reverse strand). Ensembl gene ENSG00000211695.
Subcellular location: Cell membrane
Gene Ontology:
Molecular function: MHC protein binding; peptide antigen binding
Cellular component: external side of plasma membrane; plasma membrane
Genetic constraint (gnomAD): Missense variants: 125 observed, 147.73 expected, observed/expected ratio (o/e) 0.85, 90% interval 0.73 to 0.98. Synonymous variants: 61 observed, 59.33 expected, observed/expected ratio (o/e) 1.03, 90% interval 0.84 to 1.27.
Homologues: Orthologues: macaque TRGV9 (76% identical). Paralogues in human: TRGV10 (30% identical), TRGV11 (29% identical), TRGV1 (25% identical), TRGV8 (23% identical), TRGV2 (22% identical), TRGV3 (22% identical), TRGV4 (22% identical), TRGV5 (22% identical).
Diseases named in the same sentence as TRGV9 in open-access papers:
TRGV9 is named in the same sentence as 25 diseases in open-access papers, as found by Europe PMC text mining. Sharing a sentence is not in itself a finding about the gene and the disease. The quoted sentences say what the papers report.
lung adenocarcinoma (1 paper, 2024). A carcinoma that arises from the lung and is characterized by the presence of malignant glandular epithelial cells. "In summary, the expression of TRGV9 appears to be closely associated with the clinical prognosis of patients with lung adenocarcinoma." (PMID 38297377, 2024). "Collectively, our analyses offer preliminary evidence supporting a potential causal relationship between the TRGV9 gene and lung adenocarcinoma." (PMID 38297377, 2024). "Comprehensive multi-omics assessment highlighted genetic aberrations in genes, including TRGV9, correlating with heightened lung adenocarcinoma risk." (PMID 38297377, 2024). "The expression level of TRGV9 in lung adenocarcinoma patients is closely associated with clinical features, where higher expression correlates with a better prognosis." (PMID 38297377, 2024). "Our findings predominantly aligned with our preliminary hypothesis, suggesting that alterations in TRGV9 expression could modulate lung adenocarcinoma risk." (PMID 38297377, 2024). "Additionally, partial biological validation was performed, with Western blotting analysis indicating higher expression of TRGV9 in a normal cell line compared to three other lung adenocarcinoma cell lines, corroborating the results from our dataset analysis." (PMID 38297377, 2024). "In the two-sample Mendelian randomization (MR) analysis, it was observed that RNF125, CD8B, and TRGV9 exhibit no heterogeneity concerning lung adenocarcinoma (LUAD)." (PMID 38297377, 2024).
lung carcinoma (1 paper, 2024). "Mutations in CD8B were associated with an increased lung cancer risk (OR = 3.2477, 95% CI: 1.0978–9.6079), while mutations in TRGV9 were linked to a reduced risk (OR = 0.3977, 95% CI: 0.2313–0.6837)." (PMID 38297377, 2024). "We explored the association between three genes, namely RNF125, CD8B, and TRGV9, and lung cancer risk." (PMID 38297377, 2024).
prostate carcinoma (1 paper, 2023). A carcinoma that arises from epithelial cells of the prostate gland. "Our analyses identified that TRGV9 transcripts were highly expressed compared to other TRGV genes, suggesting that Vγ9Vδ2 T cells may be enriched in prostate cancer, and particularly in bone metastases." (PMID 37134157, 2023).
tumor (17 papers, 2012 to 2025). "Through an analysis of TCGA-LUAD and its associated clinical information, we observed higher expression of TRGV9 in normal tissues compared to tumor tissues." (PMID 38297377, 2024). "In the tumor microenvironment, suppression of TRGV9 expression results in T cells failing to recognize tumor antigens, thereby reducing their effector functionality." (PMID 38297377, 2024). "Three approaches were adopted to assess the ability of anti-TRGV9 targeting bispecific antibodies in redirecting Vγ9+ γδ T cells obtained from AML patients to kill tumor cells." (PMID 33526858, 2021). "In fact, in mouse tumor models, overexpression of TRGV9 enhances T cell cytotoxicity against tumor." (PMID 38297377, 2024). "However, only the expression level of TRGV9, but not TRDV1, was correlated with TCF7, a stem‐like T cell marker in tumor tissues." (PMID 40091603, 2025).
TRGV9 also shares sentences with these, for which no sentence is quoted: infection (21 papers); viral infection (14); cancer (11); Hyponatremia (3); breast carcinoma (2); HIV-1 infection (2); nephrogenic diabetes insipidus (2); Pancreatic Cancer (2); adenocarcinoma (1); adenoma (1); breast tumour (1); co-infection (1); demyelination (1); heart failure (1); Hypertension (1); ovarian tumor (1); Pancreatic (1); prostate tumors (1); psoriasis (1); Sepsis (1); Stroke (1).